TNF (tumor necrosis factor)
Diseases named in the same sentence as TNF in open-access papers (continued):
Sharing a sentence is not in itself a finding about the gene and the disease.
viral infection (continued). "The PI3 kinase inhibitor LY294002 did not inhibit the induction of either TNF or IL-1β in response to vMyxM013-KO virus infection, indicating that this pathway is not critical for induction of either cytokine in response to vMyxM013-KO virus infection." (PMID 19851467, 2009). "Thus, RIG-I-mediated co-induction of TNF and type I IFN by virus-infected pHMs represents a novel innate defense mechanism to restrict viral infection in human cells." (PMID 18617992, 2008). "This is supported by the observation that neither expression of IL-1b nor TNFα (not shown) is significantly induced upon virus infection." (PMID 18989459, 2008). "Therefore, the increased TNF-α, IFNγ, NF-κB, and iNOS immunoexpression observed in the SARS-CoV-2-infected seminiferous epithelium confirms a pro-inflammatory response of this epithelium to the viral infection." (PMID 41596343, 2026). "Comparison of the impact of viral infection on blood and BAL dendritic cell subsets demonstrated that HTLV-1A/CoI-L infection resulted in higher levels of myeloid dendritic cells (mDCs) and plasmacytoid dendritic cells (pDCs) producing IL-8 or TNF-α in blood compared to HTLV-1A." (PMID 41006234, 2025). "Our biochemical assays showed that human N4BP1 is targeted by 3Cpro for cleavage at glutamine 816 (Q816), which impairs its regulatory function in tumor necrosis factor alpha (TNFα)-triggered NF-κB-related inflammatory signaling but does not affect viral infection in tissue culture." (PMID 39655957, 2025). "To explore whether the essential role of RIPK1 in ZBP1 activation during viral infection involves TNF signaling, we treated HT29-hZBP1 cells with or without TNF-neutralizing antibody during HSV-1(ICP6mut) infection." (PMID 39982916, 2025). "KEGG pathway analysis identified enrichment in pathways related to viral infection, cancer, tight junctions, PI3K-Akt signaling, actin cytoskeleton regulation, cGMP-PKG signaling, Hippo signaling, and TNF signaling, suggesting that SIRT7 may regulate GPS infection via these signaling pathways." (PMID 40636259, 2025). "Similarly, viral infection also induces the expression of several pro-inflammatory cytokines, including interleukin 6 (IL–6), interleukin 10 (IL–10), interferon β(IFN–β), and tumor necrosis factor α (TNF–α), all of which are significantly increased at the protein level." (PMID 39941149, 2025). "Upon virus infection, AM produce interferons (IFN) to restrict viral replication especially in the early stages of infection as well as other pro-inflammatory cytokines and chemokines such as tumor-necrosis factor α (TNFα), interleukin 6 (IL-6) and interleukin 8 (IL-8)." (PMID 39543713, 2024). "Moreover, it was reported that tumor necrosis factor (TNF)-induced programmed necrosis was facilitated by TNFR-2 signaling and caspase inhibition, and may play a role in controlling viral infection." (PMID 36849530, 2023). "The best-studied trigger of necroptotic cell death is TNFα; however, necroptosis can also be initiated by other members of the TNFα death ligand family, such as Fas ligand and TNF-related apoptosis-inducing ligand, as well as interferons, Toll-like receptor signaling, and viral infections." (PMID 36902572, 2023). "During bacterial and viral infections, local sensor cells in respiratory tract, including airway epithelia cells, alveolar macrophages and dendritic cells, firstly response to pathogens and secret the first-order cytokines, such as type I and III IFN, IL-6, TNF-α, IL-12, IL-25, IL-33, IL-1β, etc.." (PMID 38029253, 2023). "In response to viral infections, the generation of a pro-inflammatory response includes the activation of numerous transcription factors, including NF-κB, and the secretion of numerous pro-inflammatory cytokines and metabolites, including TGF-β, IL-1, IL-6, IL-11, and TNF-a." (PMID 36677504, 2023).
viral infection (continued). "A significant characteristic of severe viral infections such as SARS and COVID‐19 is a cytokine storm, which involves the release of major inflammatory factors like interleukins, interferon‐gamma (IFN‐gamma), tumor necrosis factor‐α (TNF‐α), and other cytokines." (PMID 38107099, 2023). "However, we detected no further induction of IFN-α after virus infection despite a surge of pro-inflammatory responses (IL-6, IL-1β, TNF-α, IFN-γ CCL2, CCL3, and CXCL10) compared to mature hamsters." (PMID 37122119, 2023). "Overexpression of tumor necrosis factor-α, interleukin-8 and so on have been reported in the inflammatory response of HFRS, which also confirmed that the inflammatory response of the body was involved in the circulating storm of inflammatory factors triggered by viral infection." (PMID 37215590, 2023). "Even though CLEC2.Fc was unable to inhibit virus infection and replication, CLEC2.Fc inhibited the expression of IL‐6, CXCL2, CXCL5, CCL2, and IP‐10 at day 3 and day 5 post‐infection, and the expression of TNF‐α, IFN‐γ, IL‐10, and CXCL1 was also suppressed at day 5 post‐infection (red columns)." (PMID 37211986, 2023). "By combining imaging and spatial transcriptomics modalities, we show that respiratory sequelae post viral infections is, at least in part, a result of chronic IL-1β signaling downstream of aberrant interactions between CD8+ T cells and monocyte-derived macrophages, mediated by IFN-γ and TNF." (PMID 38077031, 2023). "Also, Candida cell wall components may bind to toll-like receptors (TLRs), primarily TLR-2 and TLR-4, inducing the production of tumor necrosis factor (TNF)-α and type I IFNs that eliminate viral infections." (PMID 37573268, 2023). "However, while immune responses in p38β-/- mice have been assessed in the contexts of LPS stimulation and tumor necrosis factor overexpression, they have not been assessed in the context of viral infection." (PMID 37345956, 2023). "Meanwhile, ARND also downregulated the levels of mRNA expression of proinflammatory transcription factors (NF-κB and c-Rel), proinflammatory cytokines (IL-1β, IL-6, TNF-α and CCL2) and NOS2 in vitro, which may be useful to attenuate the inflammatory response upon viral infection." (PMID 35897044, 2022). "The lack of a PCT rise in viral infections may be due to virus-stimulated production of interferon-γ by macrophages, which inhibits TNF-α in the immune response." (PMID 36301096, 2022). "Furthermore, DAE could also ameliorate viral infection through regulation of the levels of cytokines (IFN-γ, TNF-α, and IL-4) in PRV-infected mouse serum." (PMID 36699332, 2022). "Therefore, a strategy that reduces IL-1β, IL-6, and TNF-α levels can control allergic asthma with or without viral infections." (PMID 36501052, 2022). "Additionally, whether viral infections in IBD can impact MHC-II expression is uninvestigated, particularly in the context of TNF." (PMID 35655783, 2022). "Also, co-infection of avian pathogenic E.coli and AIV-H9N2 virus can elevate the inflammatory mediators (TNF-α and INF-γ), and the immunosuppressive effect of E.coli infection decreases the birds response to the virus infection and potentiates the losses from the co-infection process." (PMID 35836502, 2022). "Firstly, data on virus antibodies and proinflammatory cytokines (e.g., interleukin [IL]-1, IL-6, IL-8 and tumor necrosis factor-α) were not available, which would provide a proper insight into the pathophysiological stage of the myocardial injury from viral infection to the immune reaction." (PMID 33664674, 2021). "Indeed, while inflammatory cytokine production was negligible (IL-1β, TNFα) or not significantly increased (IL-6), the production of IL-10 and of TNFRs was significantly enhanced upon viral infection." (PMID 34901152, 2021).
viral infection (continued). "Primary SARS-CoV-2 respiratory infection induces systemic inflammation (CXCL10, IFN-ɤ, IL-1B, IL-6, IL-8, IL-17, TNF-α) that can impact the musculoskeletal system through the expression of hACE2-R and TMPRSS2 genes in various types of musculoskeletal cells, allowing direct viral infection." (PMID 33919537, 2021). "In addition, the damage to endothelial cells after viral infection and/or activation of endothelium by pro-inflammatory cytokines, such as IL-1β, IL-6, IFN-γ, IL-8, and TNF-α induces platelets and monocyte aggregation in the vascular wall and expression of tissue factor (TF)." (PMID 33357215, 2020). "Consequently, viral infection may disrupt the secretion of interferon, IFNG, INFGR1, and TNF genes upregulated in HPV-positive CRC tissues as compared to HPV-negative CRC tissues in this study." (PMID 32258125, 2020). "Given that IFNγ, IL-1β and TNFα are upregulated by PBMC following co-culture with S. thermophilus 285 this suggests that S. thermophilus 285 induces powerful defense against invading pathogens and could be beneficial against virus infection and tumours." (PMID 32045425, 2020). "Specifically, we found that: 1) young children with high miR-155 nasal levels during viral infection had increased production of pro-inflammatory cytokines (TNF-α, IL-1β); and 2) the individuals with the highest levels of TH1 cytokine polarization had higher TNF-α and IL-1β levels." (PMID 32442188, 2020). "Both doses of GTD could enhance the secretion of IFN-β and IFN-α, but not TNF-α and IL-6 in macrophages after virus infection." (PMID 33776755, 2020). "Furthermore, they play a principal role in the response to viral infections mediated by the MyD88-dependent pathway, which activates NF-κB and MAPK and induces the production of inflammatory cytokines such as tumor necrosis factor α (TNF-α), IL-6 and IL-12." (PMID 32627735, 2020). "Our meta-analysis of TNF, TNFR1 and TNFR2 mRNA expression in RNA-seq datasets in the SRA extended a previous study of TNF, indicating its implication in the immune response by showing that mRNAs of both TNF and TNFR1 are induced in spleen and in immune cells upon virus infection and LPS treatment." (PMID 31514326, 2019). "ELISA analysis showed that IL-1β and IL-18 secretion was markedly augmented in Park2−/− cells relative to WT counterparts after viral infection, whereas the production of tumor necrosis factor (TNF)-α, an inflammasome-independent cytokine, was not affected by Park2 deletion." (PMID 31229895, 2019). "Another study indicated that Mtb is able to induce the production of TNF-α and IL-1β in RAW264.7 cells and that it activates the NF-κB pathway through TLR2-mediated signaling, thereby contributing to the induction of IRF-1, one of the most potent ISGs against viral infection." (PMID 30717477, 2019). "The transcription factor NF-κB acts a key role in the process of immune response and it can usually be activated when exposed to inflammatory cytokines such as TNF-α, viral infection, ultraviolet irradiation, and other physiological and nonphysiological stimuli." (PMID 30941197, 2019). "In viral infection, virus-positive hepatocytes are eliminated by activated circulating CD8+ T-cells either directly recognizing antigen on hepatocytes or indirectly via LSEC-mediated cross-presentation of infected hepatocytes and consequent tumor necrosis factor (TNF) release." (PMID 29643856, 2018). "B cells are increasingly recognized as being an important source of a number of cytokines in viral infections and other settings, among which both TNF-α and IL-6 could have potent noncytolytic antiviral activity against HBV." (PMID 30091725, 2018). "However, it is downregulated by TNFα or TLR stimulation as a negative feedback mechanism during viral infection." (PMID 30740112, 2018). "The role of TNF during viral infection is controversial and not sufficiently understood." (PMID 29142134, 2018).
viral infection (continued). "Interestingly, unlike our peptide stimulation assay, viral infection did not appear to stimulate CD8+ or CD4+ T cells to make TNF-α above background levels in any of the assay conditions." (PMID 28643775, 2017). "We utilized the previously established viral infection model of SVCV in zebrafish, in which excess Tnfa had already been reported to increase viral susceptibility, to dissect the possible negative role of TNFα for the host during SVCV infection." (PMID 27351838, 2016). "Besides their ability to robustly and rapidly produce IFN, human pDCs produce proinflammatory cytokines, such as tumor necrosis factor α (TNF α) and interleukin 6 (IL-6), and secrete a list of chemokines to coordinate the attraction of various immune effectors in response to viral infection." (PMID 25077037, 2014). "On the other hand, a person who does not carry the TNF-hypersensitivity trait may not become diabetic, whether or not exogenous stimuli such as a systemic viral infection occurs." (PMID 24466329, 2014). "Moreover, TNF has been shown to be critical in enhancing the CD8 T cell response to weak tumor antigens, but is less important in the CD8 T cell response in a more robust acute viral infection model with lymphocytic choriomeningitis virus (LCMV) Armstrong." (PMID 23874808, 2013). "To date, there is no certainty about the risk of reactivation, but, according to our findings, the relative safety of anti-TNF and the lack of direct hepatotoxicity encourage its use in PsA patients resistant or intolerant to conventional DMARDs and with occult or inactive viral disease." (PMID 23606869, 2013). "Due to the versatile effects of TNF, combination of TNF-overexpression and experimental infection with a neurotropic virus such as BDV is perfectly suitable to analyze the effect of elevated TNF levels on the pathogenesis and outcome of neurotropic virus infections." (PMID 22848506, 2012). "TNF-α treatment either pre- or post-infection did not cause an increase in GFP expression and remained undetectable in HIV-1 infected HFA, while Jurkat cells showed substantial increases in viral infection as demonstrated by GFP positivity." (PMID 23078780, 2012). "While we observe minor decreases in the proportion of memory CD8 T cells in lymph nodes of mice lacking help, we find that these cells are not impaired in production of IFN-γ, TNF-α, or IL-2, as has been demonstrated for helpless T cells in viral infection models." (PMID 22046294, 2011). "In time-series experiments profiling genome-wide lipid-associated gene expression of macrophages, we show a selective and coordinated negative regulation of the complete sterol pathway upon viral infection or cytokine treatment with IFNγ or β but not TNF, IL1β, or IL6." (PMID 21408089, 2011). "However, the expression levels of MHC class I molecules may also increase in response to some viral infections and inflammatory stimuli such as type 1 and 2 interferons (IFN) and tumor necrosis factor-alpha (TNF-α)." (PMID 21179539, 2010). "To determine if IκBα was stable in cells when the stimulus was not virus infection, and to confirm that p-IκBα was stable, we tested whether TNFα induced IκBα degradation in infected cells." (PMID 19180189, 2009). "Thus, the sequential involvement of IRF3 and IRF7 in the early and later phase of TNF production allows us to postulate that, if the early phase production of TNF and type I IFN is sufficient to block viral infection, then the later phase production of both cytokines will be coordinately curtailed." (PMID 18617992, 2008). "Therefore, it is likely the production of IL-6, TNF-α and IFN-β by chorion cells in response to influenza virus infection plays a beneficial role in the innate immune mechanisms against the virus infection through the induction of monocyte differentiation to mature macrophages." (PMID 19936095, 2007).
viral infection (continued). "In particular, TNFα concentration per se enables the recognition of COPD exacerbations due to Pseudomonas Aeruginosa infection, while IL8 + IL1β levels prove helpful in discriminating common bacterial infection from viral infections and noninfectious causes." (PMID 17034639, 2006). "Similarly, other studies showed that TNF-α may not be essential for in vivo control of some acute virus infections." (PMID 41282468, 2025). "Furthermore, SARS-CoV-2 infection induces several proinflammatory cytokines such as TNFα, interleukin (IL) -1, and IL-6, and activates the NLR family pyrin domain containing 3 (NLRP3) inflammasome pathway which is important for the host’s defense during viral infection." (PMID 36417106, 2022). "Here, we reported that epigenetic remodeler ARID1A, a critical component of the mSWI/SNF complex, could bind IRF3 and then was recruited to the Ifn-I promoter by IRF3, thus selectively promoting IFN-I but not TNF-α, IL-6 production in macrophages upon viral infection." (PMID 34315861, 2021). "However viral infection of the PBMCs with ZIKV or DENV again failed to induce TNF-α production." (PMID 28643775, 2017). "However in our study both the TLR agonists induced IL-6 and TNF-α secretion at early and late time points (6 hr and 16 hr) which suggests the possible protective immune response mediated by TLR agonists via secretion of pro-inflammatory cytokines during active viral infection." (PMID 25965265, 2015). "Intravenous, but not intranasal, administration of anti-TNF-α antibodies to mice significantly reduced pulmonary TNF-α levels and improved survival after the Delta P80 virus infection compared to control group, without affecting pulmonary viral load." (PMID 39652608, 2024). "Although there were individual variations, expression of neuropathic cytokines such as TNF-α, MCP-1, and IL-6 was observed in the brains infected with the Large virus, whereas almost no cytokine detection occurred in cases of Small virus infection." (PMID 39081248, 2024). "In contrast, most of viral infections do not induce PCT synthesis due to the production of interferon-gamma (INF-γ), which inhibits TNF-alpha production and, hence, PCT synthesis." (PMID 39195007, 2024). "In the absence of viral infection, a temperature switch from 18°C to 28°C for CIK cells, or grass carp in the fish tank, significantly induced the expression of IL6, IL1β, and TNF-α." (PMID 37099596, 2023). "Individuals with aggressive forms of the viral disease and an enhanced SARS-CoV-2 viral load have an absence of IFN-β, low IFN-α activity, high TNF and IL-6, and high viral load." (PMID 36406478, 2022). "Moreover, it has also been reported that GITR interaction stimulates antiviral responses through enhanced TNF-α and IFN-γ production in vivo, which may also, at least partially, contribute to explaining the systemic effects of MIM observed in the murine model of viral infectious disease." (PMID 35008536, 2021). "Concerning mechanism, we found that the transcription of TNF-α was increased in PRV-infected PK-15 cells, whereas classical RIPK1 was not related to necroptosis during viral infection." (PMID 34149651, 2021). "According to our study, the viral infection–induced up-regulation of ISG56, TNF-α, IL-8 was all down-regulated by the TTO, even recover to normal level." (PMID 34869732, 2021). "Our study provides a case for the inhibition of the TNF-α axis; TNF-α is highly expressed in alveolar macrophages, and anti–TNF-α does not block immune responses in animal models of viral infection." (PMID 32661059, 2020). "The levels of the anti-inflammatory cytokine IL-10 and of the proinflammatory cytokines IL-5, TNF-α, IFN-γ, and GM-CSF increased after viral infection in both groups, regardless of 25(OH)D3 intake." (PMID 32635656, 2020).